FUS (FUS RNA binding protein)
Diseases named in the same sentence as FUS in open-access papers (continued):
Sharing a sentence is not in itself a finding about the gene and the disease.
neurodegenerative disease (continued). "They report that, in yeast, potentiated Hsp104 variants potently suppressed toxicity induced by wild-type TDP-43, FUS and α-synuclein, as well as toxicity induced by missense mutant versions of these proteins that cause neurodegenerative disease." (PMID 25062688, 2014). "Importantly, ribonucleoproteins that participate in phase separation, such as transactive response DNA-binding protein 43 (TDP-43) and fused in sarcoma (FUS), also are enriched in protein inclusions associated with neurodegenerative diseases." (PMID 38666616, 2024). "However, certain RBPs are clear targets in their own right, such as TDP-43 and FUS, for which pathological mutations have been identified in specific neurodegenerative diseases." (PMID 38033386, 2023). "This phenomenon extends beyond β-amyloid and tau, with interactions of sleep impairment with the homeostasis of TDP-43, α-synuclein, FUS, and huntingtin proteins, implicating sleep loss as an important consideration in an array of neurodegenerative diseases and in cases of mixed neuropathology." (PMID 37085942, 2023). "This pioneering study demonstrates that FUS is directly implicated in the splicing regulation of this new class of RNAs and paves the way to elucidate the circRNAs’ role in the pathogenesis of neurodegenerative diseases in which FUS is mainly involved such as FTD and ALS." (PMID 35456950, 2022). "In addition, TDP-43 and FUS are linked to the pathogenesis of neurodegenerative diseases since they form cytoplasmic inclusions in neurons of ALS or FTD patients." (PMID 36497190, 2022). "Prolonged physiological stress and/or mutations in genes coding for TDP-43 and FUS can lead to enhanced stress granule formation, which could accelerate the pathological aggregation of these proteins in neurodegenerative diseases." (PMID 34573116, 2021). "Given mutations in FUS associate with ALS pathogenesis, LLPS of FUS may also contribute to the etiology of neurodegenerative diseases." (PMID 34306032, 2021). "Here, we establish that potentiated Hsp104 variants possess broad substrate specificity and, in yeast, suppress toxicity and aggregation induced by wild-type TDP-43, FUS and α-synuclein, as well as missense mutant versions of these proteins that cause neurodegenerative disease." (PMID 25062688, 2014). "In this way, the results of this study may advance the current knowledge of the mechanisms of biomolecular condensate formation involving a key DNA damage sensor, PARP1, and the RNA binding protein FUS, whose cellular functions are closely associated with neurodegenerative diseases." (PMID 39596510, 2024). "As the existence of LLPS foci, such as FUS, which are formed by phase separation, is implicated in neurodegenerative diseases, the presence of similar compartments in cancers, such as EML4‐ALK+ NSCLC, could also contribute to the progression and aggressiveness of the disease." (PMID 34661367, 2021). "Although emergency particle assembly and prion proliferation has been confirmed, whether FUS mutations associated with neurodegenerative diseases cause normal function loss, a gain of toxic properties of FUS aggregates, or a combination of the both requires clarification and further studies." (PMID 31022909, 2019). "Chromosomal rearrangements involving FUS, EWSR1, or TAF15 drive multiple cancers, and mutations in the genes encoding the FET proteins are associated with neurodegenerative disease." (PMID 42051291, 2026). "Increasingly, the liquid‐to‐solid transition of proteins linked to neurodegenerative diseases—such as RNA‐binding proteins TDP‐43 and FUS, as well as Tau and α‐synuclein—has emerged as a critical factor in disease pathogenesis." (PMID 40729735, 2025). "As a member of the FET family of RBPs, FUS is known for its involvement in the development of certain neurodegenerative diseases and cancers." (PMID 39113127, 2024).
neurodegenerative disease (continued). "This included two known proteins associated with MERCS, MFN2 and TOMM40, as well as neurodegenerative disease-associated genes such as WIPI2, CLASRP, BAG6, SOD1 and FUS which increase MERCS and MTCH2 and PARL which decrease MERCS." (PMID 38467609, 2024). "Here, we discuss the LLPS of four major proteins in neurodegenerative diseases: α‐synuclein, fused in sarcoma (FUS), tau, and TAR DNA‐binding protein 43 (TDP‐43)." (PMID 39006762, 2024). "Currently, the research focus of HNRNP P2 is mainly in neurodegenerative diseases; however, it is noteworthy that FUS also shows oncogenic properties." (PMID 39366930, 2024). "While this review is primarily focused on four specific proteins, these trends can be observed in other IDPs associated with neurodegenerative diseases such as TIA-1, hnRNP, FUS, ataxin, and SOD1." (PMID 36834792, 2023). "Proteins that are associated with neurodegenerative diseases, such as Tau, TDP-43, and FUS, have the propensity to undergo phase separation and to aggregate within the droplets." (PMID 37100792, 2023). "Behavioural Variant Frontotemporal Dementia (bvFTD) is a neurodegenerative disease characterized by the pathological accumulation of proteins including tau, TAR DNA-binding protein 43 (TDP-43) and fused in sarcoma (FUS) protein amongst others." (PMID 36340772, 2022). "Aberrant function of several RNA binding proteins including TAR DNA-binding protein 43 (TDP-43), Fused in Sarcoma (FUS) and Senataxin (SETX) has been linked to neurodegenerative disease pathogenesis." (PMID 35321094, 2022). "Fused in Sarcoma (FUS) is a nuclear RNA/DNA binding protein that mislocalizes to the cytoplasm in the neurodegenerative diseases ALS and FTD." (PMID 35581240, 2022). "This is distinctly different from disease-causing mutations in IDR-containing RBPs that have been linked to neurodegenerative disease such as TDP-43, FUS, or hnRNP-A1, which lead to the formation of metastable, then stable, pathological inclusions." (PMID 35202393, 2022). "Several neurodegenerative diseases have been associated with the aggregation of RNA-binding proteins, including TAR DNA binding protein of 43 kDa (TDP-43) and fused in sarcoma (FUS)." (PMID 33748125, 2021). "Thus, manipulation of the lysosome dynamics and activity may represent a possible therapeutic strategy for delaying disease progression in ALS cases associated with FUS mutations and related neurodegenerative diseases where proteins able to phase separate could form aberrant insoluble aggregates." (PMID 34746121, 2021). "The implication of mutations of the RNA-binding domain of FUS in the etiologies of neurodegenerative diseases suggests that the RNA binding ability of FUS is necessary to maintain neuron functionality." (PMID 33947944, 2021). "In light of the widely recognized role of FUS mutations in neurodegenerative diseases such as ALS and FTLD, it is important to shed new light on FUS function also in neurophysiological processes." (PMID 34299185, 2021). "Mutations in RBPs that affect SG biology, including FUS, TDP-43, hnRNPA1, hnRNPA2B1, and TIA1, underlie ALS, IBM, and other neurodegenerative diseases." (PMID 34291734, 2021). "In neurodegenerative diseases such as ALS, ALS-related FUS mutations, predominantly within the nuclear localization signal (NLS) domain, often lead to its cytoplasmic mislocalization (30, –, 32)." (PMID 33827951, 2021). "Previous studies have shown that FUS plays an important role in age-related diseases, such as neurodegenerative diseases, by forming liquid compartments at sites of DNA damage and in the cytoplasm upon stress in cell." (PMID 32041309, 2020). "In yeast, galactose-inducible expression of several proteins associated with neurodegenerative diseases, including αSyn, TDP-43, and FUS results in their cytoplasmic aggregation and toxicity." (PMID 33319748, 2020).
neurodegenerative disease (continued). "ALS is a neurodegenerative disease, which implies that, although mutant FUS is ubiquitously expressed, ALS pathology has a certain degree of cell-type specificity." (PMID 30937520, 2019). "FUS has also been recently reported to localize within nuclear phase separated assemblies, while mutations in its N-terminal low complexity (LC) regions impair this distribution, linking FUS to the establishment of neurodegenerative disease like ALS." (PMID 31238957, 2019). "RNA binding proteins (RBPs) such as transactive response (TAR) DNA-binding protein 43 (TDP-43), and fused in sarcoma (FUS) genetically and pathologically link the two neurodegenerative diseases to a single disease state." (PMID 29774215, 2018). "Among the four RBPs tested, only TDP-43 and FUS form cytoplasmic inclusions in neurons of patients affected by neurodegenerative diseases such as ALS." (PMID 29728455, 2018). "This process plays a key role in regulating inflammatory responses across a variety of cell types, and has been found to be central in the FUS mutation of ALS as well as other neurodegenerative diseases." (PMID 30618638, 2018). "Mutations in various RNA binding proteins such as hnRNP A1, hnRNP A2/B1, FET protein family (FUS, TAF-15, EWSR1) Matrin-3, TIA-1 and Ataxin-244 are implicated in various neurodegenerative diseases." (PMID 29070802, 2017). "Proteins involved in RNA processing, including FUS and TDP-43, have a nuclear localization and are linked to neurodegenerative diseases such as amyotrophic lateral sclerosis." (PMID 26423724, 2015). "Fused in sarcoma (FUS) is an RNA-binding protein involved in pathogenesis of several neurodegenerative diseases." (PMID 24842888, 2014). "As a hub protein FUS is indeed a critical node; dysregulation of FUS adversely affects RNA metabolism at multiple levels and results in neurodegenerative disease." (PMID 23967011, 2013). "Although the mammalian prion protein PrP lacks this domain, other neurodegenerative disease proteins such as FUS (Fused in Sarcoma) and TDP-43 (TAR DNA-binding protein 43) have been shown to contain Q/N-rich prion-like domains." (PMID 23555277, 2013). "Similar to proteinaceous inclusions typical for certain neurodegenerative diseases, both cytoplasmic and nuclear inclusions in neurons of FUS-TG mice were resistant to proteinase K treatment (A and A′)." (PMID 23867462, 2013). "The suppression by TAF15 is specific to FUS and not found in other yeast models of neurodegenerative disease-associated proteins." (PMID 42187823, 2026). "TDP-43 and FUS proteins are also involved in other neurodegenerative diseases." (PMID 41465426, 2025). "This converging pathway may be highly relevant in both TDP-43-mediated and FUS-mediated neurodegenerative diseases." (PMID 40468389, 2025). "This study provides essential information in understanding the role of RNA secondary structure and FUS–RNA interactions in biology, particularly for neurodegenerative diseases, and identifies rG4s as unique targets for the development of novel therapeutics for FUSopathies." (PMID 41029441, 2025). "Furthermore, mutant FUS molecules are prone to forming cytoplasmic aggregates, a common sign of various neurodegenerative diseases." (PMID 40430041, 2025). "The phosphorylation of serine residues significantly strengthens the solubility of the FUS protein in patients with neurodegenerative disorders, which may have implications for targeted therapy of neurodegenerative diseases." (PMID 39366930, 2024). "Using the power of the RF model, we carefully reviewed FDA-approved drugs for neurodegenerative diseases to see if they could be effective against the FUS protein." (PMID 39975842, 2024). "Interestingly, FUS and TDP-43, along with their mutants, can undergo mislocalization and aggregation, implicated in various neurodegenerative diseases beyond ALS and FTD." (PMID 38029395, 2024).
neurodegenerative disease (continued). "Moreover, we found an association of PARP1 activity with the formation and genesis/maturation of FUS-rich cytoplasmic inclusions, which are found in neurons of patients affected by certain major neurodegenerative diseases, including ALS." (PMID 36497190, 2022). "Interestingly, several RNA-binding proteins involved in neurodegenerative diseases have been implicated in the maintenance of DNA integrity in response to DNA damage, including TDP-43, FUS, hnRNPA1, and Ataxin-2." (PMID 35187086, 2022). "Since FUS mislocalization and aggregation are observed in patients with various neurodegenerative diseases, we hypothesized that partial FUS cytoplasmic mislocalization in FusΔNLS/+ mice could be sufficient to cause a number of behavioral phenotypes." (PMID 34021132, 2021). "For example, one study investigating the functions of FUS and autophagy in neurodegenerative diseases revealed that FUS could mediate the cell autophagy during the progression." (PMID 32907536, 2020). "Interestingly, most of these proteins are neurodegenerative disease-implicated proteins such as tau, TDP-43, and FUS." (PMID 32998269, 2020). "lncRNAs have been implicated in neurodegenerative diseases dependent on alterations in RNA metabolism because a large number of them are dysregulated upon the depletion of RNA-binding proteins causing FTLD and/or ALS, such as FUS and TDP4327." (PMID 29142303, 2017). "We also present the complete list of human proteins with PrLDs and discuss the prevalence of the PrLD in nucleic-acid binding proteins that are often connected to neurodegenerative disease, including: ataxin 1, ataxin 2, FUS, TDP-43, TAF15, EWSR1, hnRNPA1, and hnRNPA2." (PMID 26996412, 2016). "How might the incorporation of mutant-FUS into stress granules alter cellular homeostasis under conditions of induced stress, and what are the implications for neurodegenerative disease?" (PMID 24090136, 2013). "Cytoplasmic aggregation of wild-type FUS was subsequently reported as the prominent disease phenotype in other neurodegenerative diseases such as basophilic inclusion body disease, some types of juvenile ALS, and in the majority of tau- and TDP43-negative FTLD." (PMID 22724023, 2012). "Notably, mutations in SG-associated genes—including MAPT, TARDBP (TDP-43), FUS, ATXN2, TIA1, and HNRNPA1—have been shown to disrupt SG dynamics, impair disassembly, and enhance aggregation propensity, thereby contributing to neurodegenerative disease pathogenesis." (PMID 41278186, 2025). "Thus, FUS mislocalization in our model may serve as a sensitive marker for transport dysfunction and early pathological changes relevant to neurodegenerative disease contexts." (PMID 40970514, 2025). "However, a transition to the (largely irreversible) insoluble amyloid state has been observed for other neurodegenerative disease related proteins such as FUS in amyotrophic lateral sclerosis and increasingly discussed in relation to other neurodegenerative disease proteins." (PMID 36373666, 2022). "FUS phosphorylation at its IDR could disrupt its phase separation and cytoplasmic aggregation, which reduces FUS-associated cytotoxicity, suggesting that FUS is a potential therapeutic target in the treatment of neurodegenerative diseases." (PMID 35628304, 2022). "The role of SFPQ, in concert with FUS, in maintaining the isoform ratio of tau, a primary component of neurofibrillary tangles in the neurodegenerative diseases, further interweaves the intricate network of SFPQ with other neurodegenerative disease-linked RBPs." (PMID 32998269, 2020). "Notably, in neurodegenerative diseases, FUS forms cytoplasmic inclusions that can be toxic by themselves or may impair the DNA-related function of nuclear FUS in ALS or FTLD patients." (PMID 32987654, 2020).
neurodegenerative disease (continued). "In metabolic-active neurons, disruption of the cell homeostasis may induce the dissociation of polysomes and the formation of RNA-rich aggregates containing RNA-binding proteins like TDP-43 or FUS, which may act as a critical step in neurodegenerative diseases." (PMID 25013173, 2014). "Stress granule assembly and functions are related to neurodegenerative diseases, for example, pathological TDP-43 and FUS aggregates show disturbance of Stress granule assembly and biological functions." (PMID 40409555, 2025). "C9orf72-specific up-regulated protein change revealed the involvement of the TOR pathway (online resource), meanwhile FUS and SOD1 shared common features in terms of RNA processing and neurodegenerative diseases-related pathways (online resource)." (PMID 37488208, 2023). "Mislocalization of nuclear proteins to the cytosol occur in several neurodegenerative diseases, where RNA-binding proteins such as TDP-43, Tau, and FUS can aberrantly localize to the cytosol where they become more prone to aggregation." (PMID 37061046, 2023). "It has been proposed that Hsp104 has the therapeutic potential to protect higher eukaryotes against the toxic effects of neurodegenerative disease substrates, such as TDP-43, FUS, and α-synuclein." (PMID 37446010, 2023). "NIR cargos, such as FUS, TDP-43, and hnRNPA1, which are IDR-containing RBPs, can undergo liquid–liquid phase separation and are involved in different neurodegenerative diseases." (PMID 36101390, 2022). "Recently, the involvement of IDPs, such as FUS, hnRNPA1, and TDP43, in the pathology of neurodegenerative diseases has attracted considerable attention." (PMID 35682906, 2022). "It is an intrinsically disordered protein that generates intracellular foci, similar to other neurodegenerative disease proteins such as TDP43, FUS, and hnRNPs." (PMID 35682906, 2022). "The PrLDs have been identified in about 240 human proteins, especially many RNA-binding proteins, such as FUS, EWSR1, TDF-43 and TAF15 that are etiologically related to several neurodegenerative diseases, including frontotemporal dementia and ALS." (PMID 35628304, 2022). "We have a good appreciation that the dysregulation of protein folding and condensation can result in human disease, as is well-exemplified by multiple neurodegenerative diseases, for example, ectopic aggregates containing TDP-43 and FUS in ALS." (PMID 33898525, 2021). "Genes that contribute to FTD include: C9ORF72, FUS, VCP, TDP–43, MAPT/tau, CHMP2B, PGRN, TBK1, and TMEM106B, thus there is overlap with other neurodegenerative diseases including: ALS (C9ORF72, FUS, VCP and TDP–43), AD (tau) and PD (tau)." (PMID 32357532, 2020). "As for TDP-43, mislocalization and inclusions of FUS are not limited to ALS and FTLD but have also been detected in other neurodegenerative diseases, including Huntington disease." (PMID 30992467, 2019). "In the past few years, several different RBPs have been identified demonstrating their altered functions and aggregation properties in neurodegenerative diseases, among which TDP-43, FUS and TIA-1 are extensively studied." (PMID 30367664, 2018). "In this study, we confirmed that GLE1 knock-down reduces the cytoplasmic mRNA expression of some genes, like FUS and HDAC1, which participate in neurodegenerative disease." (PMID 29746542, 2018). "It will be important to determinewhether any of these RRM-bearing proteins, aside from FUS and TDP-43, areconnected to neurodegenerative disease." (PMID 21541367, 2011). "This scenario would imply that putative FUS filaments behave differently to filaments of tau, α-synuclein, TDP-43 and Aβ, which characterize most cases of neurodegenerative disease and which were all previously shown to be extracted from human brain using the method used in this study." (PMID 38057661, 2024).